COL17A1 (collagen type XVII alpha 1 chain)
Diseases named in the same sentence as COL17A1 in open-access papers (continued):
Sharing a sentence is not in itself a finding about the gene and the disease.
colorectal cancer (7 papers, 2016 to 2025). A primary or metastatic malignant neoplasm that affects the colon or rectum. "For example, COL17A1 is overexpressed in colorectal cancer and exerts oncogenic activity in disease malignant progression." (PMID 39143031, 2024). "As an example, in colorectal cancer, upregulated COL17A1 promotes disease progression by elevating the expression of immunosuppressive cytokines." (PMID 39143031, 2024). "This study demonstrated that upregulation of NEIL1 enhances colorectal cancer initiation through the formation of an RNA polymerase II transcriptional complex with SATB2 and cMyc, which drives COL17A1 expression leading to cancer-associated immunosuppression." (PMID 38779538, 2024). "For instance, COL17A1 could mediate dormancy of colorectal cancer cells via FAK-YAP signaling and induce chemoresistance of colorectal cancer." (PMID 39376555, 2024). "Another study focusing on tumor-initiating cells found increased levels of COL17A1 in a STAT-3–dependent manner, which correlated inversely with survival in patients with colorectal cancer." (PMID 40728119, 2025). "We then examined specimens from 150 colorectal cancer patients and showed an increase in phosphorylation at S727 of STAT3 and Col17a1 expression in correspondence with tumour stages, and the expression of these two markers inversely correlated with patient survival." (PMID 27306323, 2016).
epithelial recurrent erosion dystrophy (7 papers, 2016 to 2024). Epithelial recurrent erosion dystrophy (ERED) is a rare form of superficial corneal dystrophy characterized by recurrent episodes of epithelial erosions from childhood in the absence of associated diseases, with occasional impairment of vision. "Almost all the variants in COL17A1 caused epithelial recurrent erosion of dystrophy (ERED), except for a sporadic case with homozygous variant c.3554C>T, p.(Pro1185Leu), which presented FECD." (PMID 36902444, 2023). "Mutations in COL17A1 cause epithelial recurrent erosion dystrophy; however, the corneal epithelium of this patient was normal." (PMID 31555324, 2019). "Epithelial recurrent erosion dystrophy (ERED) is caused by mutation in the COL17A1 gene." (PMID 37174680, 2023). "COL17A1 mutations have been associated with dominantly inherited epithelial recurrent erosion dystrophy (ERED), aberrant Collagen XVII expression is implicated in the early atypia/malignant transformation of keratinocytes." (PMID 29156757, 2017). "Despite recognition that heterozygous carriers in JEB families can have AI, and that heterozygous COL17A1 variants also cause dominant corneal epithelial recurrent erosion dystrophy (ERED), the importance of heterozygous COL17A1 variants causing dominant non-syndromic AI is not widely recognised." (PMID 37979963, 2024).
cervical cancer (6 papers, 2016 to 2023). A primary or metastatic malignant neoplasm involving the cervix. "For example, in patients with epithelial cancers such us breast and cervical cancer aberrant COL17A1 promoter methylation is predictive of poor prognosis." (PMID 37803411, 2023). "Aberrant Col17A1 promoter methylation can predict the prognosis of patients with epithelial cancers, such as breast and cervical cancers." (PMID 31928533, 2020). "Some studies have shown upregulated COL17A1 in ductal breast cancers, prostate carcinoma, cutaneous squamous cell, and basal cell carcinomas and in cervical cancer and squamous cell carcinomas." (PMID 33381179, 2020). "In contrast, COL17A1 is hypomethylated and upregulated in cervical cancer, head, neck, and lung squamous cell carcinoma, and lung adenocarcinoma." (PMID 31612115, 2019). "But COL17A1 was over-expressed and its promoter was hypo-methylated in cervical cancer and other epithelial cancers." (PMID 29340021, 2017). "In contrast to breast tumors, cervical cancers show a significant twofold increase in COL17A1 mRNA level compared to normal control tissue (p = 0.0046, Mann-Whitney U test, n = 185)." (PMID 27891193, 2016). "Interestingly, the COL17A1 promoter methylation status correctly predicts the direction of collagen XVII misexpression in multiple types of epithelial cancers, including breast and cervical cancer." (PMID 27891193, 2016).
lung carcinoma (4 papers, 2019 to 2024). "COL17A1 is upregulated in lung cancer spheroids and required for the maintenance of CSC characteristics and EMT phenotypes; works with laminin 332 to maintain CSC characteristics and EMT phenotype in lung cancer." (PMID 31334229, 2019).
psoriasis (4 papers, 2018 to 2025). An autoimmune condition characterized by red, well-delineated plaques with silvery scales that are usually on the extensor surfaces and scalp. "The predominant psoriasis-associated cluster (cluster 0) exhibited high COL17A1 expression, potentially linked to selection pressures under proliferative signals." (PMID 40537825, 2025).
glioblastoma multiforme (3 papers, 2017 to 2025). "To further explore the biological relevance of COL17A1 expression in GMB pathogenesis, we analyzed gene expression data of 87 Primary Glioblastoma multiforme (pGBM) patients and 22 recurrent GBM (rGBM) patients obtained from CGGA." (PMID 29156757, 2017). "A recent study showed that a novel PTEN-COL17A1 fusion gene is involved in regulating COL17 expression and glioblastoma multiforme (GBM) aggressiveness and determined that COL17A1 may play the roles of a prognostic biomarker and potential therapeutic targets of GBM." (PMID 33381179, 2020).
lung adenocarcinoma (3 papers, 2016 to 2024). A carcinoma that arises from the lung and is characterized by the presence of malignant glandular epithelial cells. "We also find that the COL17A1 promoter is hypomethylated in head and neck squamous cell carcinoma, lung squamous cell carcinoma, and lung adenocarcinoma, in all of which collagen XVII overexpression has previously been shown." (PMID 27891193, 2016). "In lung adenocarcinoma cells, the deubiquitinase USP22 stabilizes COL17A1 protein by enhancing COL17A1 deubiquitination to upregulate COL17A1 and thus promotes cell growth, invasion, and migration and suppresses cell apoptosis and ferroptosis, leading to this disease progression." (PMID 39143031, 2024).
pancreatic adenocarcinoma (3 papers, 2007 to 2023). "We used immunohistochemistry to assess the expression of COL17A1 protein in 169 paraffin-embedded pancreatic adenocarcinomas and 67 adjacent normal specimens." (PMID 33381179, 2020). "COL17A1 is known to be overexpressed in many malignancies, such as pancreatic adenocarcinoma, and promoting cell multiplication and cell apoptosis inhibition, by activating the NF-κB pathway, may have a role in cancer development and progression." (PMID 37109658, 2023). "However, little knowledge is available on the expression and prognostic value of COL17A1 in pancreatic adenocarcinoma (PDAC)." (PMID 33381179, 2020). "These genes include many not previously associated with pancreatic adenocarcinoma, such as galectin-4 (LGALS4), mucin 13 (MUC13), secretory leukocyte protease inhibitor (SLPI), collagen 17A1 (COL17A1), and ropporin 1-like (ROPN1L)." (PMID 17389914, 2007). "However, the expression and biological significance of COL17A1 in pancreatic adenocarcinoma has not been reported yet." (PMID 33381179, 2020).
squamous cell carcinoma (3 papers, 2020 to 2023). A carcinoma arising from squamous epithelial cells. "Abnormal expression of the COL17A1 gene has been detected in many epithelial tumors such as colorectal (CRC), pancreatic, breast, cervical or squamous cell carcinoma and associated with poor prognosis." (PMID 37803411, 2023). "In skin cancers like squamous cell carcinoma (SCC), immunohistochemical analysis has shown a correlation between the presence of type XVII collagen in the primary tumor and metastasis and increased expression of COL17A1 was associated with poor survival in patients with CRC." (PMID 37803411, 2023).
alopecia (2 papers, 2023 to 2025). Hair loss usually from the scalp. "Biallelic inactivating mutations in COL17A1 cause intermediate junctional epidermolysis bullosa 4, a genetic disorder characterized by skin blisters and erosions, nail dystrophy, and alopecia." (PMID 37835579, 2023).
atopic dermatitis (2 papers, 2023). "The proband of family 1, with hypoplastic pitted AI and mild localized atopic dermatitis, had compound heterozygous COL17A1 mutations (paternal NM_000494.4: c.3598G>T, p.Asp1200Tyr and maternal c.1700G>A, p.Gly567Glu)." (PMID 37888105, 2023). "The analysis revealed that the proband of family 1 had autosomal recessive hypoplastic AI and mild localized atopic dermatitis caused by hypomorphic COL17A1 missense mutations." (PMID 37888105, 2023). "The proband of family 1 had irregular pitted hypoplastic AI and localized atopic dermatitis, and compound heterozygous missense COL17A1 mutations were identified." (PMID 37888105, 2023).
breast invasive carcinoma (2 papers, 2017 to 2023). "Moreover, low COL17A1 expression was significantly associated with a shorter median survival time among patients with breast invasive carcinoma." (PMID 28915553, 2017). "Moreover, high COL17A1 expression was associated with longer survival of patients with invasive breast carcinoma." (PMID 28915553, 2017). "An analysis of metastasis breast invasive carcinoma revealed that each patient demonstrates different expression levels of COL17A1 in different tissue types depending on the tumor progression." (PMID 28915553, 2017). "COL17A1 inhibits cancer cell migration and invasion by inactivating AKT/mTOR pathway, and its over-expression is linked with longer survival in patients with invasive breast cancer." (PMID 36936416, 2023).
breast tumor (2 papers, 2016 to 2017). "In summary, we elucidated the role of COL17A1 as a breast tumor metastasis suppressor by inhibition of cancer cell migration and invasion, resulting in a better prognosis of patients." (PMID 28915553, 2017). "This revealed that the COL17A1 promoter is indeed hypermethylated in breast tumors (n = 735 tumors, n = 92 normal samples; p < 0.0001, Mann-Whitney U test) and this hypermethylation is independent of COL17A1 allelic copy number variations (p < 0.0001)." (PMID 27891193, 2016).
corneal dystrophy (2 papers, 2016). The term corneal dystrophy embraces a heterogeneous group of bilateral genetically determined non-inflammatory corneal diseases that are usually restricted to the cornea. "However, the recent association of another corneal dystrophy with a synonymous substitution in COL17A1 that creates a cryptic splice donor site, resulting in the loss of 18 amino acids, highlights the potential pathogenicity of synonymous substitutions." (PMID 27355326, 2016).
Dystrophic epidermolysis bullosa (2 papers, 2021 to 2025). "Several stop-gain variants in COL7A1 and COL17A1 are identified in our study; these disrupt protein structures critical to dermal-epidermal cohesion, leading to severe dystrophic epidermolysis bullosa (DEB) phenotypes." (PMID 40956805, 2025). "Among these, mutations in COL7A1 and COL17A1 were associated with dystrophic epidermolysis bullosa." (PMID 34901026, 2021).
glioma (2 papers, 2017 to 2025). A benign or malignant brain and spinal cord tumor that arises from glial cells (astrocytes, oligodendrocytes, ependymal cells). "We also performed COL17A1 gene transfection experiments to further determine the influence of Collagen XVII expression on their invasive abilities of glioma cell lines." (PMID 29156757, 2017). "In IDH-wt glioma, PGR, COL17A1, and RGS14 showed strong predictive value for recurrence, consistent with their known roles in tumor aggressiveness and therapy resistance." (PMID 41139924, 2025). "In IDH-wt glioma, our approach identified PGR, COL17A1, and RGS14 as key predictive markers for recurrence, consistent with their known roles in tumor aggressiveness and therapy resistance." (PMID 41139924, 2025). "COL17A1 expression directly affects activated form of Rac expression, indicating that COL17A1 regulate MMP9 expression likely through GTP-Rac1 activity in glioma, Together these data demonstrated that Increased Collagen XVII expression promotes the invasive activities of glioma cells." (PMID 29156757, 2017).
lymph node metastasis (2 papers, 2020 to 2023). "Although, the significant correlation between risk genes MEOX1, COL17A1, and lymph-node metastasis in triple-negative breast cancer patients has been reported." (PMID 37178414, 2023). "We also observed a significantly positive correlation between COL17A1 expression and lymph node metastasis (p < 0.0001), TNM clinical stage (p < 0.0001), and pathology differentiation (p < 0.01)." (PMID 33381179, 2020).
preeclampsia (2 papers, 2022 to 2024). Preeclampsia is a hypertensive disorder of pregnancy that is characterized by new-onset hypertension with proteinuria presenting after 20 weeks of gestation, and depending on mild or severe forms may initially present with severe headache, visual disturbances, and hyperreflexia. "Our study identified COL17A1, FLT1, FSTL3, and SERPINA3 as novel diagnostic biomarkers for preeclampsia patients." (PMID 35528613, 2022). "COL17A1, FLT1, FSTL3, and SERPINA3 were identified as diagnostic genes of preeclampsia and validated in the GSE44711 datasets." (PMID 35528613, 2022). "The distinct upregulation of COL17A1, SERPINA3, FSTL3, and FLT1 in preeclampsia was further demonstrated." (PMID 35528613, 2022). "Our findings together with previous findings suggested COL17A1, FLT1, FSTL3, and SERPINA3 may influence the immune function of preeclampsia patients." (PMID 35528613, 2022).
aging (1 paper, 2023). A developmental process that is a deterioration and loss of function over time. "Furthermore, COL17A1 is closely linked to skin aging, as its levels significantly decrease with age." (PMID 37958946, 2023).
cervical tumors (1 paper, 2023). "Nevertheless, very few studies have shown a clear role of type XVII collagen in bladder and kidney cancer while overexpression of COL17A1 has been detected in cervical tumors." (PMID 37803411, 2023).
cholesteatoma (1 paper, 2023). A pathologic process characterized by the proliferation of keratinizing squamous epithelium resulting in the accumulation of keratin and cells in the middle ear and/or mastoid. "Interestingly, MMP10 and COL17A1 are identified by the functional enrichment and GO analysis to regulate the degradation of the ECM, perhaps indicating the ECM has an important role in cholesteatoma aetiology." (PMID 36920900, 2023).
corneal disease (1 paper, 2024). "Only three COL17A1 variants have been reported in the literature as causing the corneal disease ERED." (PMID 37979963, 2024).
dysplasia (1 paper, 2023). A usually neoplastic transformation of the cell, associated with altered architectural tissue patterns. "Altered expression of Col17 (BP180/Col17A1) during the process of oral carcinogenesis and dysplasia has been reported extensively within the literature." (PMID 37173998, 2023).
enamel hypoplasia (1 paper, 2023). "Individuals with EB caused by mutations in laminin-332 (Lama3, Lamb3, Lamc2), α6ß4-integrin (TGB4, ITGA6) gene and type XVII collagen (Col17A1) are associated with enamel hypoplasia." (PMID 37511997, 2023).
endothelial dysfunction (1 paper, 2025). In vascular diseases, endothelial dysfunction is a systemic pathological state of the endothelium (the inner lining of blood vessels) and can be broadly defined as an imbalance between vasodilating and vasoconstricting substances produced by (or acting on) the endothelium. "The set includes genes such as CLDN18, NOS2, SLC4A1, CA4, COL17A1, and SP7, many of which have been implicated in vascular inflammation, endothelial dysfunction, and extracellular matrix remodelling." (PMID 41226477, 2025).
head and neck cancer (1 paper, 2023). A primary or metastatic malignant neoplasm affecting the head and neck. "In head and neck cancer and particularly among in cancers originating from the larynx and the oral cavity, lower expression of COL17A1 in early stages during cancer development may reflect alterations on keratinocytes binding to the ECM." (PMID 37803411, 2023).
invasive ductal carcinoma (1 paper, 2020). "For validation, the feature and spatial feature plots of MAF, CD248, GJA1, LAMA3, TJP1, LAMC2, and COL17A1 demonstrated to show the location in BRCA samples, and they were highly-expressed in the invasive ductal carcinoma tissue (cluster 2, 4, 7, 9, 12)." (PMID 33585235, 2020).
ischemic stroke (1 paper, 2026). A stroke disorder caused by obstruction of blood flow to the brain, due to thrombotic (local blood clot formation) or embolic (due to a blood clot or other material traveling from another site) event. "Interestingly, 203 upregulated and 212 downregulated genes, including Krt5, Krt14, Col17a1, and Pgam1‐ps1, were shared between EC‐specific KO and Vasculotide‐treated mice, indicating mutual pathways underlying the endothelial EphA4/Tie2 axis following ischemic stroke." (PMID 41164967, 2026).
metastatic tumors (1 paper, 2017). "Similarly, COL17A1 expression was decreased in metastatic tumors compared to primary tumors and normal tissues, even from the same patients." (PMID 28915553, 2017).
Mitral regurgitation (1 paper, 2024). An abnormality of the mitral valve characterized by insufficiency or incompetence of the mitral valve resulting in retrograde leaking of blood through the mitral valve upon ventricular contraction. "COL17A1 has been linked to mitral regurgitation and mitral valve prolapse in humans." (PMID 37938355, 2024).
nail disease (1 paper, 2023). "These bear similarities to nail disease in humans with Col17a1 mutation induced JEB, but are not evident in either B6-Col17a1em1/em1 or B6-Lamc2jeb/jeb parental strains." (PMID 37883475, 2023).
orofacial cleft (1 paper, 2023). A disorder of facial skeleton that is characterized by cleft lip and/or cleft palate that result in feeding, speech and hearing problems caused by failures during development. "Additionally, a rare, likely pathogenic variant of COL17A1 has been described in ns-CLP patients, suggesting that COL17A1 is a novel candidate for isolated orofacial clefts." (PMID 36902838, 2023).
rosacea (1 paper, 2026). A chronic erythematous skin disorder that affects the face. "Four key genes (ALDH1A1, COL17A1, RELL1, and ZNF404) were identified, with ALDH1A1 as a risk factor and the others as protective factors for rosacea." (PMID 42112773, 2026).
stomach adenocarcinoma (1 paper, 2023). "Similarly, COL17A1 is expressed in both normal epithelial stomach cells and stomach adenocarcinoma." (PMID 37414817, 2023).
thymoma (1 paper, 2019). A neoplasm arising from the epithelial cells of the thymus. "The amount and the percentage of thymoma containing COL17A1 was significantly (P < 0.01) higher in type AB as compared to type B2/B3." (PMID 31409307, 2019).